PRKAA2 (protein kinase AMP-activated catalytic subunit alpha 2)
Description:
Catalytic subunit of AMP-activated protein kinase (AMPK), an energy sensor protein kinase that plays a key role in regulating cellular energy metabolism. In response to reduction of intracellular ATP levels, AMPK activates energy-producing pathways and inhibits energy-consuming processes: inhibits protein, carbohydrate and lipid biosynthesis, as well as cell growth and proliferation. AMPK acts via direct phosphorylation of metabolic enzymes, and by longer-term effects via phosphorylation of transcription regulators. Regulates lipid synthesis by phosphorylating and inactivating lipid metabolic enzymes such as ACACA, ACACB, GYS1, HMGCR and LIPE; regulates fatty acid and cholesterol synthesis by phosphorylating acetyl-CoA carboxylase (ACACA and ACACB) and hormone-sensitive lipase (LIPE) enzymes, respectively. Promotes lipolysis of lipid droplets by mediating phosphorylation of isoform 1 of CHKA (CHKalpha2). Regulates insulin-signaling and glycolysis by phosphorylating IRS1, PFKFB2 and PFKFB3 (By similarity). Involved in insulin receptor/INSR internalization. AMPK stimulates glucose uptake in muscle by increasing the translocation of the glucose transporter SLC2A4/GLUT4 to the plasma membrane, possibly by mediating phosphorylation of TBC1D4/AS160 (By similarity). Acts as a key regulator of glucose homeostasis in liver by phosphorylating CRTC2/TORC2, leading to CRTC2/TORC2 sequestration in the cytoplasm (By similarity). In response to stress, phosphorylates 'Ser-36' of histone H2B (H2BS36ph), leading to promote transcription (By similarity). Acts as a key regulator of cell growth and proliferation by phosphorylating FNIP1, TSC2, RPTOR, WDR24 and ATG1/ULK1: in response to nutrient limitation, negatively regulates the mTORC1 complex by phosphorylating RPTOR component of the mTORC1 complex and by phosphorylating and activating TSC2. Also phosphorylates and inhibits GATOR2 subunit WDR24 in response to nutrient limitation, leading to suppress glucose-mediated mTORC1 activation. In response to energetic stress, phosphorylates FNIP1, inactivating the non-canonical mTORC1 signaling, thereby promoting nuclear translocation of TFEB and TFE3, and inducing transcription of lysosomal or autophagy genes. In response to nutrient limitation, promotes autophagy by phosphorylating and activating ATG1/ULK1. In that process, it also activates WDR45/WIPI4. Phosphorylates CASP6, thereby preventing its autoprocessing and subsequent activation. AMPK also acts as a regulator of circadian rhythm by mediating phosphorylation of CRY1, leading to destabilize it (By similarity). May regulate the Wnt signaling pathway by phosphorylating CTNNB1, leading to stabilize it (By similarity). Also acts as a regulator of cellular polarity by remodeling the actin cytoskeleton; probably by indirectly activating myosin. Also phosphorylates CFTR, EEF2K, KLC1, NOS3 and SLC12A1. Plays an important role in the differential regulation of pro-autophagy (composed of PIK3C3, BECN1, PIK3R4 and UVRAG or ATG14) and non-autophagy (composed of PIK3C3, BECN1 and PIK3R4) complexes, in response to glucose starvation (By similarity). Can inhibit the non-autophagy complex by phosphorylating PIK3C3 and can activate the pro-autophagy complex by phosphorylating BECN1 (By similarity). Upon glucose starvation, promotes ARF6 activation in a kinase-independent manner leading to cell migration. Upon glucose deprivation mediates the phosphorylation of ACSS2 at 'Ser-659', which exposes the nuclear localization signal of ACSS2, required for its interaction with KPNA1 and nuclear translocation. Upon stress, regulates mitochondrial fragmentation through phosphorylation of MTFR1L.
Synonyms: AMPK; AMPK2; AMPKa2; PRKAA
Tractability: Small molecule: a drug acting on it is in phase 2 or 3 trials; a structure with a bound ligand is known; a high-quality ligand is known; it has a high-quality binding pocket; it belongs to a druggable protein family. PROTAC: it is named in the literature on targeted protein degradation; UniProt records ubiquitination sites on it; ubiquitination databases record sites on it; its protein half-life has been measured; a small molecule that binds it is known.
Target class: CAMK protein kinase group; CAMK protein kinase AMPK subfamily; Protein Kinase; Enzyme; CAMK protein kinase CAMK1 family; Kinase
Safety:
Unwanted effects reported when the protein is acted on. In parentheses: how it was acted on, where the effect was seen, and who reports it.
cardiac arrhythmia (cardiovascular system; source: Lamore et al. (2017))
heart disease (cardiovascular system; source: Force et al. (2011))
Gene: Protein-coding gene on chromosome 1 (56,645,314 to 56,715,335, forward strand). Ensembl gene ENSG00000162409.
Subcellular location: Cytoplasm; Nucleus; Late endosome
Subcellular location (Human Protein Atlas): Nuclear speckles; Basal body; Cytosol; Golgi apparatus; Nucleoplasm
Pathways (Reactome):
Autophagy: Lipophagy; Macroautophagy
Metabolism: AMPK inhibits chREBP transcriptional activation activity; Carnitine shuttle
Cellular responses to stimuli: Nuclear events mediated by NFE2L2
Immune System: AMPK-induced ERAD and lysosome mediated degradation of PD-L1(CD274)
Neuronal System: Activation of AMPK downstream of NMDARs
Organelle biogenesis and maintenance: Activation of PPARGC1A (PGC-1alpha) by phosphorylation
Signal Transduction: Energy dependent regulation of mTOR by LKB1-AMPK
Vesicle-mediated transport: Translocation of SLC2A4 (GLUT4) to the plasma membrane
Gene Ontology:
Molecular function: AMP-activated protein kinase activity; protein binding; protein serine kinase activity; protein serine/threonine kinase activity; protein serine/threonine/tyrosine kinase activity; [hydroxymethylglutaryl-CoA reductase (NADPH)] kinase activity; chromatin binding; histone H2BS36 kinase activity; protein kinase activity; ATP binding
Biological process: adiponectin-activated signaling pathway; cellular response to glucose starvation; cellular response to nutrient levels; lipid droplet disassembly; negative regulation of hepatocyte apoptotic process; negative regulation of TORC1 signaling; protein localization to lipid droplet; regulation of lipid metabolic process; cellular response to calcium ion; cellular response to glucose stimulus; cellular response to oxidative stress; energy homeostasis; fatty acid homeostasis; glucose homeostasis; lipid biosynthetic process; negative regulation of apoptotic process; negative regulation of gene expression; negative regulation of TOR signaling; positive regulation of autophagy; positive regulation of glycolytic process; positive regulation of macroautophagy; positive regulation of protein localization; regulation of circadian rhythm; regulation of macroautophagy; regulation of microtubule cytoskeleton organization; and 3 more
Cellular component: nuclear speck; nucleoplasm; nucleotide-activated protein kinase complex; nucleus; axon; cytoplasm; cytoplasmic stress granule; cytosol; dendrite; endoplasmic reticulum lumen; neuronal cell body; late endosome
Genetic constraint (gnomAD): Loss-of-function variants: 28 observed, 40.33 expected, observed/expected ratio (o/e) 0.69, 90% interval 0.51 to 0.95. The upper end of that interval is the gene's LOEUF score, 0.95, which puts it in group 4 of 6, group 1 being the genes least tolerant of losing a copy. Missense variants: 472 observed, 571.66 expected, observed/expected ratio (o/e) 0.83, 90% interval 0.76 to 0.89. Synonymous variants: 185 observed, 199.17 expected, observed/expected ratio (o/e) 0.93, 90% interval 0.82 to 1.05.
Homologues: Orthologues: chimpanzee PRKAA2 (100% identical), macaque PRKAA2 (100% identical), guinea pig PRKAA2 (99% identical), dog PRKAA2 (99% identical), rat Prkaa2 (98% identical), pig PRKAA2 (98% identical), mouse Prkaa2 (98% identical), rabbit PRKAA2 (94% identical), tropical clawed frog prkaa2 (94% identical), zebrafish prkaa2 (89% identical), Drosophila melanogaster AMPKalpha (64% identical), Caenorhabditis elegans C27D6.11 (18% identical), and 2 more. Paralogues in human: PRKAA1 (77% identical), SIK2 (33% identical), SIK3 (31% identical), SIK1 (30% identical), BRSK2 (30% identical), BRSK1 (30% identical), MELK (29% identical), NUAK2 (29% identical), NUAK1 (28% identical), SNRK (27% identical), HUNK (24% identical), NIM1K (22% identical), and 5 more.
Diseases named in the same sentence as PRKAA2 in open-access papers:
PRKAA2 is named in the same sentence as 130 diseases in open-access papers, as found by Europe PMC text mining. Sharing a sentence is not in itself a finding about the gene and the disease. The quoted sentences say what the papers report.
breast carcinoma (25 papers, 2014 to 2025). "Changes in PRKAA2 expression have been linked to the occurrence, development, and prognosis of multiple tumor types, including breast cancer, ovarian cancer, gastric cancer, kidney cancer, and liver hepatocellular carcinoma." (PMID 38424484, 2024). "Consistent with our findings in EC, elevated LMO3 expression has been associated with poor prognosis in gastric cancer and neuroblastoma, PRKAA2 in endometrial cancer and RAB10 in breast cancer and hepatocellular carcinoma." (PMID 40804485, 2025).
Obesity (20 papers, 2013 to 2025). Accumulation of substantial excess body fat. "In obese in vivo models and individuals with obesity, the expression of Cs, Sirt3, and Prkaa2 is reduced and is associated with mitochondrial dysfunction." (PMID 39269560, 2025).
Insulin resistance (16 papers, 2011 to 2025). Increased resistance towards insulin, that is, diminished effectiveness of insulin in reducing blood glucose levels. "Moreover, chronic sodium restriction increased the expression of markers of liver insulin resistance (G6pc and Pck1) and reduced the expression of transcription factors associated with oxidative metabolism (Prkaa2 and Ppara)." (PMID 36978847, 2023). "The LS diet increased the expression of genes related to insulin resistance (ApocIII, G6pc, Pck1) and reduced those involved in oxidative capacity (Prkaa1, Prkaa2, Ppara, Lipe) and lipoprotein assembly (Mttp)." (PMID 34202724, 2021).
Hypertension (14 papers, 2013 to 2025). The presence of chronic increased pressure in the systemic arterial system. "In this work, we observed, for the first time, that that maternal melatonin therapy prevents hypertension associated with increased expression of Sirt1, Sirt4, Prkaa2, Prkab2, Pparg, and Ppargc1a in adult offspring kidneys." (PMID 29641494, 2018). "Hypertension programmed by a maternal methyl-donor diet is associated with the reduced expression of nutrient-sensing signaling in several forms, including Sirt1, Pparb, Pparg, and Prkaa2." (PMID 32545526, 2020). "Another study demonstrated that maternal melatonin therapy prevented a hypertension programmed high-fructose/high-salt diet by regulating Sirt1, Sirt4, Prkaa2, Prkab2, Pparg, and Ppargc1a." (PMID 31766163, 2019). "Hypertension programmed by a maternal methyl-donor diet is related to decreases in several forms of nutrient-sensing signaling, including Sirt1, Prkaa2, Pparb, and Pparg." (PMID 31766163, 2019). "RNF207 had no significant variants, and PRKAA2 was linked to several phenotypes involving myocardial ischemia, hypertension, and lipid metabolism." (PMID 37723491, 2023).
atherosclerosis (12 papers, 2011 to 2024). A disease characterized by the build-up of fatty material and calcium deposition in the arterial wall resulting in partial or complete occlusion of the arterial lumen. "Our previous study showed that Prkaa2 knock out (AMPKα2−/−) are more prone to atherosclerosis (AS) than Prkaa1 knock out (AMPKα1−/−) mice model." (PMID 36513627, 2022).
type 2 diabetes (11 papers, 2017 to 2026). "In clinical research, PRKAA2 has been shown to be associated with susceptibility to type 2 diabetes, In addition, the high expression of PRKAA2 may predict the poor prognosis of head and neck squamous cell carcinoma, colorectal cancer, and endometrial cancer." (PMID 36672854, 2022).
colorectal cancer (9 papers, 2020 to 2023). A primary or metastatic malignant neoplasm that affects the colon or rectum. "In addition, the high expression of PRKAA2 may indicate a poor prognosis in head and neck squamous cell carcinoma and colorectal cancer." (PMID 37671041, 2023). "In addition, high expression of PRKAA2 may predict poor prognosis in head and neck squamous cell carcinoma and colorectal cancer (CRC)." (PMID 34170849, 2021).
diabetes (9 papers, 2012 to 2025). "Another anti-aging and diabetes drug, metformin, primarily targets mitochondrial respiration, but also mediates longevity by regulating insulin-like growth factor (IGF-1) and AMP-activated protein kinase (AMPK; also known as PRKAA2) signaling." (PMID 34345916, 2021).
gastric cancer (7 papers, 2017 to 2025). A primary or metastatic malignant neoplasm involving the stomach. "PRKAA2, also known as AMPKα2, can regulate autophagy-related genes to mediate autophagy at the transcriptional level, thus promoting drug resistance in gastric cancer cells." (PMID 39895782, 2025). "CircCPM regulates gastric cancer 5‐FU chemoresistance through the miR‐21‐3p/ PRKAA2 axis." (PMID 35075806, 2022). "PRKAA2 plays a key role in regulating autophagy and 5-FU resistance in gastric cancer." (PMID 36120466, 2022). "Pharmacological interference of ULK1 and PRKAA2 as therapeutic targets might provide a novel therapeutic strategy to target gastric cancer cells, which are resistant to cisplatin/5-FU treatment." (PMID 28109268, 2017).
prostate carcinoma (7 papers, 2013 to 2025). A carcinoma that arises from epithelial cells of the prostate gland. "However, contradictory results were observed in some other cancer types, such as gastric and prostate cancer, which indicated that PRKAA2 was a protective gene in cancer development by upregulating the expression of hypoxia-inducible factor-1α and hepatocyte nuclear factor 4α." (PMID 31761783, 2019).
melanoma (6 papers, 2016 to 2025). A malignant, usually aggressive tumor composed of atypical, neoplastic melanocytes. "To test the relevance of our finding that Treg cells upregulate Prkaa2 in the TME, we bred Treg cell–specific AMPKα1-deficient (Prkaa1fl/flFoxp3YFP–Cre) and AMPKα2-deficient (Prkaa2fl/flFoxp3YFP–Cre) mice and evaluated their response to B16 melanoma tumor grafts." (PMID 40100289, 2025). "Recently it has been reported that knockout of PRKAA2 in NF1-deficient melanoma cells promoted anchorage-independent growth in vitro, as well as growth as xenografts in immunodeficient mice in vivo, suggesting that AMPK-α2 can act as a tumour suppressor in that context." (PMID 37962491, 2023). "The context-specific upregulation of Prkaa2 in tumor-infiltrating Treg cells may explain the discrepant consequences for antitumor immunity reported in Treg cell–specific AMPKα1-deficient mice challenged with B16 melanoma tumors." (PMID 40100289, 2025). "Our results show that almost half (47%) of the mutations in the PRKAA2 gene that have been reported in cases of human skin cancer and melanoma cause partial or total loss-of-function, reinforcing the hypothesis that such mutations are being selected for in these cancer types." (PMID 37962491, 2023). "For the PRKAA2 gene in skin cancer and melanoma, the database also contained five nonsense mutations, eight frameshift mutations and two mutations expected to cause splicing errors, making 15 mutations that would all be expected to cause a total loss in AMPK-α2 function." (PMID 37962491, 2023). "However, very few of the mis-sense mutations in PRKAA2 that occur in human skin cancer and melanoma have been tested to see whether they cause loss-of-function." (PMID 37962491, 2023). "While we did not detect Prkaa2 expression in splenic and lymph node Treg cells of mice bearing subcutaneous B16 melanoma tumor grafts, we found that control Treg cells upregulated the expression of Prkaa1 and Prkaa2 in the TME." (PMID 40100289, 2025). "Further analysis also revealed that Pdcd1 was negatively correlated with AMPK subunit mRNAs including Prkaa1, Prkaa2, and Prkag1 in TCGA database obtained from prostate, melanoma, and breast cancer patients." (PMID 34649584, 2021). "In addition, knockout of PRKAA2 in NF1-mutant melanoma cells increased their growth as xenografts in immunodeficient mice, and increased the presence of metastases in brain when they were administered by intracardiac injection." (PMID 37962491, 2023). "While this study was in progress, Zheng's group showed that knockout of PRKAA2 in NF1-mutant melanoma cells promoted anchorage-independent growth in soft agar, while ectopic expression of PRKAA2 in NF1- and AMPK-α2-deficient human melanoma cells greatly reduced this." (PMID 37962491, 2023). "Finally, knockout of PRKAA2 in NF1-mutant melanoma cells increased their growth as xenografts in immunodeficient mice, and increased the presence of metastases in brain when they were administered by intracardiac injection." (PMID 37962491, 2023). "Interestingly, the PRKAA2 gene encoding AMPK-α2 displays mis-sense mutations in 10–20% of cases of certain cancers (for reasons that remain unclear, this was particularly common in skin cancer and melanoma)." (PMID 36383046, 2022).
colon carcinoma (5 papers, 2017 to 2020). "No report was available for the COLEC12 transcript, whereas PRKAA2 was shown to promote colon cancer." (PMID 28962550, 2017).
left ventricular hypertrophy (5 papers, 2010 to 2023). Enlargement of the LEFT VENTRICLE of the heart. "For instance, Prkaa2-KO mice show no cardiac alteration, and these mice show exacerbated pressure overload–induced left ventricular hypertrophy only under stress conditions." (PMID 35230976, 2022).
Hypoglycemia (4 papers, 2022 to 2025). A decreased concentration of glucose in the blood. "SF-1 stimulates baseline VMNdm Ghrh neuron PRKAA1/AMPKα1 and PRKAA2/AMPKα2 gene expression, yet causes opposite changes in these gene profiles during hypoglycemia." (PMID 39401164, 2024). "Relative PRKAA2 gene expression was augmented by hypoglycemia in GABA nerve cells from both VMN locations." (PMID 38902332, 2024).
ischemia (4 papers, 2019 to 2025). A hypoperfusion of the BLOOD through an organ or tissue caused by a PATHOLOGIC CONSTRICTION or obstruction of its BLOOD VESSELS, or an absence of BLOOD CIRCULATION. "As a subunit of the heterotrimeric AMP-activated kinase (AMPK) complex, PRKAA2 (also known as AMPKα2) regulates glucose and lipid metabolism, especially during ischemia." (PMID 37723491, 2023).